IGHV1-69D (immunoglobulin heavy variable 1-69D)
Description:
V region of the variable domain of immunoglobulin heavy chains that participates in the antigen recognition. Immunoglobulins, also known as antibodies, are membrane-bound or secreted glycoproteins produced by B lymphocytes. In the recognition phase of humoral immunity, the membrane-bound immunoglobulins serve as receptors which, upon binding of a specific antigen, trigger the clonal expansion and differentiation of B lymphocytes into immunoglobulins-secreting plasma cells. Secreted immunoglobulins mediate the effector phase of humoral immunity, which results in the elimination of bound antigens. The antigen binding site is formed by the variable domain of one heavy chain, together with that of its associated light chain. Thus, each immunoglobulin has two antigen binding sites with remarkable affinity for a particular antigen. The variable domains are assembled by a process called V-(D)-J rearrangement and can then be subjected to somatic hypermutations which, after exposure to antigen and selection, allow affinity maturation for a particular antigen.
Gene: Immunoglobulin variable (V) gene on chromosome 14 (106,762,092 to 106,762,588, reverse strand). Ensembl gene ENSG00000280411.
Subcellular location: Secreted; Cell membrane
Gene Ontology:
Molecular function: antigen binding
Biological process: immunoglobulin mediated immune response
Cellular component: extracellular region; plasma membrane
Homologues: Orthologues: mouse Ighv1-50 (66% identical), mouse Ighv1-55 (66% identical), mouse Ighv1-74 (66% identical), mouse Ighv1-53 (65% identical), mouse Ighv1-64 (65% identical), mouse Ighv1-81 (65% identical), mouse Ighv1-61 (64% identical), mouse Ighv1-69 (64% identical), mouse Ighv1-80 (64% identical), mouse Ighv1-4 (63% identical), mouse Ighv1-52 (63% identical), mouse Ighv1-66 (63% identical), and 47 more. Paralogues in human: IGHV1-69 (99% identical), IGHV1-18 (81% identical), IGHV1-3 (81% identical), IGHV1-2 (79% identical), IGHV1-46 (78% identical), IGHV1OR15-1 (78% identical), IGHV1-45 (77% identical), IGHV1-58 (76% identical), IGHV1-24 (75% identical), IGHV1-69-2 (73% identical), IGHV1OR21-1 (73% identical), IGHV1OR15-9 (72% identical), and 65 more.